IGFBP1 (insulin like growth factor binding protein 1)
Diseases named in the same sentence as IGFBP1 in open-access papers (continued):
Sharing a sentence is not in itself a finding about the gene and the disease.
breast carcinoma (continued). "Taken together, these data support the conclusion that IGFBP-1 is a key component of the development of tamoxifen resistance in breast cancer cells." (PMID 32435229, 2020). "The impact that [D-glucose] had on GPER1-dependent tamoxifen action in breast cancer cells was demonstrated by measuring the accumulation of IGFBP-1 expression in tamoxifen-treated breast cancer cells in the presence of increasing [D-glucose]." (PMID 31242463, 2019). "Previous studies revealed that mTOR, HOXA1, and IGFBP1 were targeted by miR-99a in breast cancer; FGFR3 was targeted by miR-99a in bladder cancer; in the present study, we identified FGFR3 as a direct target of miR-99a in breast cancer for the first time." (PMID 32038996, 2019). "The addition of G-36 significantly reduced the Tam-stimulated increase in IGFBP-1 transcript level in breast cancer cells cultured in 0 mM D-glucose." (PMID 31242463, 2019). "We previously reported that 4-hydroxytamoxifen (Tam), the active metabolite of tamoxifen, induces the expression of IGFBP-1 in a GPER1-dependent manner in MCF-7 breast cancer cells." (PMID 31242463, 2019). "The gene cluster included TFF1, PGR, GREB1, and other ER-sensitive genes such as insulin-like growth factor binding protein 1 (IGFBP1), breast carcinoma amplified sequence, and fibulin." (PMID 23938070, 2013). "In this context, IGFBP-1 inhibits the growth of breast cancer cells in mice with MCF-7 breast cancer xenografts, as well as hepatocellular cancer growth in mice over-expressing IGF-I and IGF-II." (PMID 24073332, 2013). "EGR1 is a transcription factor that acts as a tumor suppressor in breast cancer cells, whereas IGFBP1 regulates cell proliferation by binding to and inhibiting IGF1 effects." (PMID 22848683, 2012). "Exogenously added IGF binding protein I (IGFBP-1) inhibits IGF-I mediated growth of breast cancer cells." (PMID 20051100, 2010). "No consistent interactions were observed among variants in the IGF1, IGFBP1, and IGFBP3 genes with any of the following: first-degree family history of breast cancer, ever oral contraceptive use, use of postmenopausal hormones, and BMI (<25, 25-<30, 30+)." (PMID 18596909, 2008). "Numerous recent epidemiologic studies have begun to examine variation in the genes encoding IGF1, IGFBP1, and IGFBP3 in relation to breast cancer risk." (PMID 18596909, 2008). "Our study is by far the largest to examine genetic variation in the IGF1, IGFBP1, and IGFBP3 genes in relation to both circulating IGF-I and IGFBP-3 levels and breast cancer risk." (PMID 18596909, 2008). "Our findings are consistent with two previous studies that comprehensively examined the role of IGF1, IGFBP1, and IGFBP3 genetic variation in relation to circulating IGF-I and IGFBP-3 levels and breast cancer risk." (PMID 18596909, 2008). "Other studies have primarily examined individual variants in IGF1, IGFBP1, or IGFBP3 in relation to breast cancer with mixed results." (PMID 18596909, 2008). "We comprehensively examined the association between common genetic variation in the IGF1, IGFBP1, and IGFBP3 genes in relation to circulating IGF-I and IGFBP-3 levels and breast cancer risk within the NCI Breast and Prostate Cancer Cohort Consortium (BPC3)." (PMID 18596909, 2008). "Upon treatment with Ful, IGFBP-3 was induced in breast cancer cells similar to data observed in reports describing the regulation of IGFBP-1 by the G-protein-coupled estrogen receptor (GPER1) and clinical studies showing IGFBP-3 serum increases in response to Ful." (PMID 39619437, 2024). "In breast cancer cells, estrogen regulates IGFBP1 expression via GPER1." (PMID 37907850, 2023). "Given that both of the MCF7-BP1 and T47D-BP1 had higher levels of EGFR, phospho-EGFR, and phospho-Erk, it was hypothesized that the long-term exposure to IGFBP-1 was sufficient for the development of tamoxifen resistance in breast cancer cells." (PMID 32435229, 2020).
breast carcinoma (continued). "Taken together, these data indicated that the sustained exposure to IGFBP-1 results in increased EGFR signaling in breast cancer cells and this transition to EGF sensitivity is similar to the transition that occurs during development of tamoxifen resistance in breast cancer cells." (PMID 32435229, 2020). "Data from these reports supports a tumor suppressive role for IGFBP-1 in breast cancer cells." (PMID 32435229, 2020). "Furthermore, these data suggest that elevated IGFBP-1 levels stimulate Erk activation and resulting in tamoxifen resistance in breast cancer cells." (PMID 32435229, 2020). "Based on these data, we hypothesized that [D-glucose]-dependent changes in GPER1 expression alter the IGFBP-1-dependent tamoxifen response of breast cancer cells." (PMID 31242463, 2019). "The results from these experiments reveal that D-glucose deprivation increased GPER1-mediated and tamoxifen-induced IGFBP-1 transcription suggesting that [D-glucose] may increase breast cancer cell sensitivity to tamoxifen." (PMID 31242463, 2019). "Results from epidemiologic studies indicate that higher circulating levels of IGF-I are associated with increased risk of breast cancer but do not support an association between IGFBP-1 and breast cancer." (PMID 26251693, 2015). "Given that IGFBP-1 possesses tumor suppressive roles in breast cancer, its down-regulation in malignant seroma suggest that it might be involved in promoting malignant tumor progression." (PMID 26361584, 2015). "To comprehensively examine the role of common genetic variation in the IGF1, IGFBP1, and IGFBP3 genes in relation to circulating IGF-I and IGFBP-3 levels and breast cancer risk, we conducted a haplotype-based analysis in the NCI Breast and Prostate Cancer Cohort Consortium (BPC3)." (PMID 18596909, 2008). "Association of tagging SNPs of IGFBP1 and IGFBP3 and breast cancer risk in the BPC3." (PMID 18596909, 2008). "However, in the tamoxifen resistant breast cancer cell the role for IGFBP-1 has been altered." (PMID 32435229, 2020). "Fulvestrant has been shown to modulate IGFBP-1 levels in vitro and IGFBP-3 levels in the serum of breast cancer patients." (PMID 39619437, 2024). "In breast cancer cells, 4-OHT suppresses IGF-1 signaling due to the accumulation of extracellular IGFBP1, which is mediated by GPER1 and CREB." (PMID 37907850, 2023). "Exercise program alone in breast cancer patients also found improvements in IGF-1, IGFBP-1 and IGFBP-3 in maintenance of BMD." (PMID 36839371, 2023). "Other BPs such as IGFBP-1, IGFBP-2, and IGFBP-5 also play a role in breast cancer, but were outside the scope of this study." (PMID 33767994, 2021). "IGFBP-1 is anti-proliferative for MCF-7 cells and T-47D cells was demonstrated to inhibit the mobility of human metastatic breast cancer cell line MDA-231BO." (PMID 32435229, 2020). "In GSE70905, YTHDC1 (p < 0.05), IGFBP1 (p < 0.001), ALKBH5 (p < 0.001), WTAP (p < 0.001), YTHDF3 (p < 0.001) and HNRNPA2B1 (p < 0.001) were down-regulated in breast cancer to the adjacent." (PMID 33362863, 2020). "Previously, we showed that 4-hydroxytamoxifen (Tam) induces the expression of insulin-like growth factor-binding protein 1 (IGFBP1) via a GPER1-dependent mechanism in MCF-7 and SkBr-3 breast cancer cells." (PMID 31242463, 2019). "IGFBP1 and IGFBP3 genes are located adjacent to each other and are important regulators of bioavailability of IGF-1, which stimulates proliferation of breast cancer cell lines and primary culture." (PMID 30400783, 2018). "Consistent with its physiological function, in breast cancer IGFBP-1 has also been shown to inhibit IGF-mediated cell proliferation and breast cancer cell motility." (PMID 26361584, 2015). "A differential change between E+P and E-alone in IGFBP1 was supported by ELISA data in an independent set of 50 subjects for each regimen and may provide an important lead to understanding clinical effects that differ between the two preparations, including breast cancer." (PMID 20034393, 2009).
breast carcinoma (continued). "IGFBP-1 is known to neutralise the actions of IGF-1, but in addition, it exerts independent actions as it inhibits breast cancer cell motility and growth by itself." (PMID 15846300, 2005). "Furthermore, these data demonstrate that sustained IGFBP-1 exposure results in tamoxifen resistance and IGFBP-1 expression is a critical component of chemoresistance in breast cancer cells." (PMID 32435229, 2020). "One explanation for the data presented here is that IGFBP-1 is expressed but not phosphorylated and therefore potentiates Erk activation in tamoxifen resistant breast cancer cells." (PMID 32435229, 2020). "While [D-glucose] altered the tamoxifen response in both MCF-7 and T-47D breast cancer cells, the IGFBP-1 induction was not exactly the same in both cell lines tested." (PMID 31242463, 2019). "While IGFBP-1 expression was not changed when [D-glucose] was varied in MCF-7 breast cancer cells, Tam-dependent IGFBP-1 induction was significantly increased in breast cancer cells when treated while D-glucose-deprived." (PMID 31242463, 2019). "We investigated the association between 89 single nucleotide polymorphisms (SNPs) in 7 cytokine/growth-factor genes (FGFR2, IGFBP1, IGFBP3, TGFB1, TNF, VEGF, IL6) and percent MD in 301 premenopausal women (aged 50 to 55 years) participating in the Norwegian Breast Cancer Screening Program." (PMID 23762340, 2013). "A similar role for IGFBP-1 in breast cancer cells has not been reported." (PMID 32435229, 2020). "Thus far, the mechanism by which IGFBP-1 acts to enhance cell viability in breast cancer cells has not been determined." (PMID 32435229, 2020). "Moreover, IGFBP1 (at concentrations of 800 ng/mL or higher) can interact with integrin receptors to induce focal adhesion kinase (FAK) dephosphorylation, and the detachment and apoptosis of breast cancer cells." (PMID 31590218, 2019). "In addition to the role that IGFBP-1 has in the activation of cellular pathways, the regulation of IGFBP-1 expression and activity will need to be investigated to include analyzing the phosphorylation status of IGFBP-1 in the tamoxifen resistant breast cancer cell context." (PMID 32435229, 2020). "However, an opposite pattern was identified for other of them (VEGFR2/KDR, CYR61/CCN1, IGFBP1, IGFBP4, IGFP6) and no changes for CTGF/CCN2, and IGFP6 across the breast cancer subtypes." (PMID 33531624, 2021). "In contrast to nontreated con cells, for senescent human breast cancer MDA-MB-231 cells, the factors detected by arrays and secreted at a significant level are FGF-6, GM-CSF, IGFBP-1, MCP-1, IL-6, IL-1α, GRO a/b/g, GRO α, IL-8, MIP, MIP-1α, uPAR, ICAM-1, and MMP-1." (PMID 30871042, 2019).
endometriosis (26 papers, 2013 to 2025). The growth of functional endometrial tissue in anatomic sites outside the uterine body. "Altered expression of IGFBP1 (Insulin-like growth factor-binding protein 1) has been found in the endometrium of women with endometriosis, suggesting a potential association." (PMID 37662927, 2023). "Reduction in HOX genes leads to downregulation of other mediators of endometrial receptivity involved in infertility associated with endometriosis, such as pinopodes, αvβ3 integrin, and IGFBP-1." (PMID 35273494, 2022). "IGFBP1, a marker of decidualization induced by progesterone and cyclic adenosine monophosphate (cAMP), is downregulated in endometriosis due to overexpression of enhancer of zeste homolog 2 (EZH2)." (PMID 41009686, 2025). "In ESCs isolated from both endometriosis patients and controls, P4 treatment (14 days) upregulates IGFBP1 and PRL expression." (PMID 40072055, 2025). "Gene expression analysis using RT-qPCR demonstrated decidual markers such as BMP2 and IGFBP1 showed increasing levels throughout Day 2 to Day 8 EPC treatment in the stromal cells with blunted induction in the endometriosis cells." (PMID 38402336, 2024). "Changes in the function of mir-542-3p and its target gene IGFBP1 have been reported to alter the decidualization of endometriosis stromal cells, affecting the metastasis and invasion of ectopic endometriosis cells." (PMID 37662927, 2023). "In mice with apparently normal endometrium, endometrial expression of Hoxa10, Hoxa11 and Igfbp1 (Insulin-like growth factor binding protein-1) was significantly reduced 14 weeks after the induction of endometriosis." (PMID 36830705, 2023). "In cases where endometriosis was implanted subcutaneously at distant sites (distal), endometrial gene expression was little affected except for Igfbp1 and PGR (p ≤ 0.02)." (PMID 36830705, 2023). "Primary hEnSCs isolated from the endometrial tissues of endometriosis patients showed impaired decidualization after differentiation stimulus, as revealed by IGFBP1 mRNA expression and secreted PRL levels." (PMID 36195592, 2022). "First, the endometrial stromal cells show a relative deficiency of progesterone-sensitive gene markers associated with endometrial stromal cell decidualization in patients with endometriosis (e.g., IGFBP1, LEFTY2, LUM, DCN, etc.)." (PMID 36104692, 2022). "Our scRNA-Seq data clearly shows the reduction of the IGFBP1+-expressing decidualized stromal cell subcluster in endometriosis cases vs. controls." (PMID 36104692, 2022). "It is striking that an apparently decidualized stromal cell subcluster (expressing IGFBP1 mRNA) is significantly enriched in controls compared with endometriosis cases." (PMID 36104692, 2022). "ME-SFCs from laparoscopically diagnosed endometriosis patients exhibit reduced decidualization capacity, measured by IGFBP1 production after exposure to cAMP." (PMID 36304708, 2020). "The similarity in IGFBP1 levels among symptomatic and endometriosis patients supports this approach." (PMID 36304708, 2020). "Using an ROC curve, defects in the decidualization capacity of ME-SFCs are strongly predictive of the presence of endometriosis (AUC = 0.92), with an optimal cut-off point of 14.2 for IGFBP1 by ELISA." (PMID 36304708, 2020). "Significantly less IGFBP-1 was produced following both vehicle-treatment and cAMP-treatment at all three time points by ME-SFCs obtained from endometriosis subjects when compared to control subjects (p < 0.05)." (PMID 30134794, 2018). "ME-SFCs obtained from endometriosis subjects produced significantly less IGFBP-1 following stimulation when compared to control ME-SFCs." (PMID 30134794, 2018). "Log of IGFBP-1 secretion at 6 h, 24 h, and 48 h of cAMP (0.5 mM) stimulation per subject (n = 7 control, n = 7 endometriosis)." (PMID 30134794, 2018). "The concentration of IGFBP-1 produced by cells in patients with both CE and endometriosis was decreased compared with the endometriosis patients without CE (P < 0.05)." (PMID 28259137, 2017).
endometriosis (continued). "During endometriosis where increase activity of this pathway is present, a decrease in the decidual marker (IGFBP1 and PRL) was observed." (PMID 28475617, 2017). "Finally, overexpression of PRMT5 rescued the defective expression of IGFBP1 and prolactin in primary endometrial stromal cells from endometriosis patients." (PMID 36195592, 2022). "Reduced decidualization and IGFBP-1 secretion have also been observed in primary endometriotic cells from other localizations and in eutopic endometrial stromal cells from women with endometriosis." (PMID 24036443, 2013). "However, IGFBP-1 shows a nearly two-fold reduction during the window of implantation in the endometrium of women with endometriosis, and its secretion by cultured endometrial stromal fibroblasts from women with endometriosis is also reduced." (PMID 37108154, 2023). "Our results showing IGF1 increasing and IGFBP1 and IGFBP4 reducing the odds for an endometriosis diagnosis suggest an opposing function of IGF1 and their binding proteins in bloods collected years prior to endometriosis diagnosis." (PMID 40215752, 2025). "Downstream progesterone-responsive genes, such as HOXA10, IGFBP1, and FOXO1, are also affected by DNA methylation and histone modifications, and are altered in endometriosis." (PMID 41009686, 2025). "Collectively, these studies demonstrate impaired decidualization capacity in eutopic ESCs from endometriosis patients, characterized by reduced expression and secretion of the decidualization markers PRL and IGFBP1." (PMID 40072055, 2025). "In this section, we focus on IGFBP1 and PRL expression dysregulation during the decidualization of ESCs from patients with endometriosis." (PMID 40072055, 2025). "The model with the lowest AIC and highest AUC was a 4-protein model including TOP1, HIST1H3A, IGFBP1, and CD5L which discriminated endometriosis cases from controls with an AUC = 0.71 (95%CI = 0.66–0.76) from the conditional logistic regression model." (PMID 40215752, 2025). "Endometrial expression of Hoxa10, Hoxa11, Igfbp1, Klf9 (Kruppel-like factor 9) and PGR was reduced in mice when endometriosis was induced in the peritoneal cavity (proximal) compared to control eutopic endometrium." (PMID 36830705, 2023). "Lastly, IGFBP1, a downstream target gene of HOXA 10 and a marker of decidualization, is reduced in the endometrium of women with endometriosis, and it is also downregulated in the eutopic endometrium of mice with induced endometriosis." (PMID 36387918, 2022). "We next analyzed the expression levels of SOX4, PGR, FOXO1, HERC4, IGFBP1, and PRL in the mid-secretory endometrium of healthy women (control, n = 12) versus women who suffered RIF due to endometriosis (EMS-RIF, n = 12)." (PMID 35244538, 2022). "Other transcriptional factors involved in regulation and mediation of progesterone signaling (IGFBP1, GATA2, FOXO1, ARID1A, NOTCH1and WNT4), required for successful implantation are also reduced in endometrium of women with endometriosis." (PMID 36387918, 2022). "Both IGFBP-1 and PRL are drastically downregulated in the eutopic endometrium of women affected by endometriosis." (PMID 32063886, 2019). "IGFBP-1 is downregulated in endometriosis via reduced levels of forkhead box O1 (FOXO1) and homeobox A10 (HOXA10), upstream target genes of IGFBP-1." (PMID 24179489, 2013). "Both Org OD 02-0 concentrations mimicked the effects of P4 by upregulating the expression of IGFBP1, PRL, HAND2, and ZBTB16 in control, eutopic, and ectopic cells from women with endometriosis, suggesting the involvement of mPRs in the decidualization process of endometrial cells." (PMID 40806428, 2025). "HDAC3 silencing in ESCs from women without endometriosis impairs in vitro decidualization, evidenced by decreased IGFBP1 and PRL expression." (PMID 40072055, 2025).